CST3 (cystatin C)
Diseases named in the same sentence as CST3 in open-access papers (continued):
Sharing a sentence is not in itself a finding about the gene and the disease.
Cognitive impairment (25 papers, 2011 to 2026). Abnormal cognition is characterized by deficits in thinking, reasoning, or remembering. "Compared with maintaining a medium level, maintaining a low level of Cystatin C was associated with a decreased risk of cognitive impairment." (PMID 41778039, 2026). "A linear and positive association was observed between cystatin C levels and the prevalence of cognitive impairment (p for linearity < 0.001)." (PMID 41743058, 2026). "Serum cystatin C is similarly thought to prevent cognitive impairment by inhibiting amyloid Aβ, a protein encoded by the CST3 gene." (PMID 38845616, 2024). "The findings of this study will help elucidate the effect of cystatin C on cognitive function among older adults, which has significant benefits in diagnostic as well as therapeutic implications for cognitive impairment among older adults." (PMID 37207178, 2023). "Cystatin C is linked to the risk of cognitive impairment through genetic and neuropathological pathways." (PMID 37207178, 2023). "Accumulating evidence has suggested that cystatin C was significantly associated with cognitive impairment in older adults, as well as patients with neurodegenerative diseases." (PMID 36518820, 2022). "Sarnak's research showed that higher levels of cystatin C were associated with cognitive impairment." (PMID 36090853, 2022). "Accumulating evidence has suggested that cystatin C is associated with cognitive impairment in patients with neurodegenerative diseases." (PMID 36518820, 2022). "It has been reported that higher levels of cystatin C were associated with cognitive impairment in neurodegenerative diseases, including AD and PD." (PMID 36518820, 2022). "A large prospective cohort study indicated that higher level of cystatin C was associated with cognitive impairment in older Chinese adults." (PMID 36518820, 2022). "In order to determine the association between serum cystatin C levels and cognitive impairment, we stratified the cohort based on the CDR grade (mild CDR = 0.5 or 1, moderate CDR = 2, severe CDR = 3)." (PMID 35153722, 2021). "The Health ABC Study showed that high levels of serum cystatin C increased the risk of cognitive impairment and individuals with higher levels of cystatin C had poorer performance on cognitive examinations." (PMID 35153722, 2021). "A risk factor for MS could be elevated cystatin C levels, which were discovered to be an independent predictor of cognitive impairment." (PMID 37299978, 2023). "A meta-analysis suggested that cystatin C could be considered as a predictor for the risk of cognitive impairment." (PMID 36518820, 2022). "A meta-analysis including 12 studies with a total of 2,433 mild cognitive impairment patients and 1,034 controls suggested that cystatin C could be considered as a predictor for the risk of cognitive impairment." (PMID 36518820, 2022). "However, serum cystatin C levels were slightly associated with severity of cognitive impairment (OR = 1.438, 95% CI 0.017–2.858, p = 0.047)." (PMID 35153722, 2021). "However, using ordinal logistic regression models, we found that serum cystatin C levels were slightly associated with cognitive dysfunction; patients with higher cystatin C levels had increased odds of severe cognitive impairment." (PMID 35153722, 2021). "Furthermore, we aim to explore whether glucose homeostasis indicators mediate the relationship between cystatin C and the risk of cognitive impairment through mediation analysis." (PMID 37056689, 2023). "One recent study provided evidence for the use of saliva samples to source biomarkers (including cystatin C) for the early detection of cognitive impairment in individuals on the AD continuum and potentially other neurodegenerative diseases." (PMID 39409080, 2024). "In our study, the cystatin C levels of the Severe-Moderate Cognitive Impairment group were higher compared to the Mild Cognitive Impairment and the Normal Cognitive groups." (PMID 38132490, 2023).
Cognitive impairment (continued). "Higher levels of LDL-C, cystatin C, and HbA1c were found in the Severe-Moderate Cognitive Impairment group." (PMID 38132490, 2023). "This study explored the mediating role of glucose homeostasis indicators in the relationship between serum cystatin C and mild cognitive impairment (MCI)." (PMID 37056689, 2023). "However, the association between cystatin C and cognitive impairment remains unclear." (PMID 37056689, 2023). "The aim of this study is to investigate the potential relationship between various glucose homeostasis indicators, cystatin C, and cognitive impairment." (PMID 37056689, 2023). "The level of cystatin C was higher in patients with Parkinson’s disease (PD) with mild cognitive impairment." (PMID 36518820, 2022). "The data clearly shows that antipsychotic drugs are not capable of attenuating numerous dysregulated systems in schizophrenia, including, for example, cystatin C which is upregulated in SZs under 40 and is correlated with cognitive deficits." (PMID 34741130, 2022). "In subgroup analysis of the 94 participants who had same-day cystatin C blood-draw and amyloid PET scan, the association with cognitive impairment remained consistent and significant (p = 0.01)." (PMID 34616751, 2021). "The Cardiovascular Health Study, a community-based longitudinal cohort of older adults (aged ≥65) with a representative sample of non-Hispanic Black participants, estimated a 1.39 greater hazard of cognitive impairment among those with cystatin C levels >1.16 vs. ≤0.90 mg/L." (PMID 37323925, 2023). "The Aging Brain Cohort (ABC) study, another large racially diverse study conducted in the United States, found that individuals with cystatin C serum levels >1.25 mg/L had 1.92 times higher odds of 7-year incident cognitive impairment with respect to those with cystatin C levels <1.0 mg/L." (PMID 37323925, 2023). "A recent review conducted a subgroup analysis based on ethnicity and revealed that the increased level of Cystatin C was associated with the risk of cognitive impairment in the Asian population but not in the Caucasian population." (PMID 37207178, 2023). "Of significance, HFS diet caused an increase in the expression of CST3, a transcript that correlates positively with cognitive impairment in the elderly, which did not occur with RSV supplementation." (PMID 27070252, 2016). "However, our group of iPD patients did not have the cognitive impairment or motor dysfunction that is associated with increased cystatin C concentration in the plasma and serum of patients suffering with PD." (PMID 39958955, 2025). "Moreover, the Osteoporotic Fractures study reported a U-shape association between serum cystatin C and cognitive impairment in elderly women, but the association no longer existed after adjusting for covariates." (PMID 35153722, 2021). "CST3 was found to correlate with age of onset in sporadic AD as well as EEG alterations in subjects with AD and mild cognitive impairment." (PMID 22191060, 2011). "Higher levels of LDL-C, cystatin C, and HbA1c were found in the Severe-Moderate Cognitive Impairment group compared to the Mild Cognitive Impairment and the Normal Cognitive groups." (PMID 38132490, 2023). "Barthel Index score, MNA-SF score, serum albumin concentrations, hemoglobin levels, and eGFRcys were significantly lower and serum cystatin C levels and percentage of patients with physical frailty and cognitive impairment were higher in patients with SF than in patients without SF." (PMID 36606289, 2022). "Cognitive impairment could have a negative impact on the daily life of patients; therefore, reducing the level of serum cystatin C may provide a new treatment for the prevention of PSCI, and it is of great significance to timely predict the occurrence of cognitive impairment." (PMID 36090853, 2022). "In addition, a previous study also found that elders with high serum cystatin C levels had higher risks of cognitive impairment whether or not they had CKD." (PMID 35153722, 2021).
Insulin resistance (24 papers, 2016 to 2025). Increased resistance towards insulin, that is, diminished effectiveness of insulin in reducing blood glucose levels. "Last, cystatin-C might, in addition to its role in kidney function, mediate an increase in other risk factors for ageing, such as anemia, insulin resistance and inflammation." (PMID 34935094, 2022). "Although whether the level of cystatin C can accurately reflect insulin resistance remains to be verified, the role of insulin signaling pathway which was found in pathway-based association analyses cannot be ignored as the genetic background of cystatin C." (PMID 34899825, 2021). "The metabolic score for insulin resistance (METS-IR) and creatinine-to-cystatin C (CCR) are promising biomarkers linked to metabolic dysfunction and muscle-renal status, respectively." (PMID 41404507, 2025). "Gender comparison revealed higher BMI, serum creatinine, cystatin C level, and insulin resistance index (HOMA-IR) in men, while average 25-OH vitamin D levels were higher in women." (PMID 37198577, 2023). "Clinical parameters including lipids profile, serum creatinine, cystatin C, fasting glucose, insulin and C-peptide levels, HbA1c values and insulin resistance (HOMA-IR) were assessed in patients with ALMS and BBS." (PMID 36506055, 2022). "Creatinine, cystatin C, lipids, fasting glucose, and insulin levels were measured, and homeostasis model assessment -insulin resistance (HOMA-IR) was calculated." (PMID 30035656, 2018). "Renal function–related measures, including estimated glomerular filtration rate (eGFR), cystatin C (CYSC), and uric acid (UA), were included as covariates because impaired kidney function has been associated with insulin resistance and increased risk of cerebrovascular events." (PMID 40667444, 2025). "Elevated insulin resistance is associated with worse glomeruli filtration, and as such Cystatin-C could be a proxy for insulin resistance." (PMID 36094936, 2022). "Also, insulin resistance may trigger the renal damages that could be early captured by higher cystatin C levels." (PMID 41280371, 2025). "The serum cystatin C may vary due to insulin resistance or inflammation." (PMID 36743175, 2022). "Thus, high cystatin C level may reflect visceral fat accumulation and increased insulin resistance." (PMID 31317040, 2019). "Serum creatinine/cystatin C (Cr/CysC), a biomarker for skeletal muscle mass, has not been well studied in relation to insulin resistance (IR)." (PMID 40948869, 2025). "Therefore, elevated non-GFR determinants of cystatin C may represent the response to adipose tissue remodeling and the progression of insulin resistance." (PMID 31317040, 2019).
myocardial infarction (24 papers, 2011 to 2025). Gross necrosis of the myocardium, as a result of interruption of the blood supply to the area, as in coronary thrombosis. "Our study aimed to assess the association between serum cystatin C levels and prognosis in acute myocardial infarction (AMI) patients after coronary reconstructive surgery." (PMID 35392813, 2022). "Specifically, increased levels of cystatin C, serpin F2, and CD14 were correlated with an increased risk of myocardial infarction, vascular events, and mortality." (PMID 37293281, 2023). "In participants with intermediate cystatin C-GRS, elevated plasma cystatin C concentrations were associated with an increased risk of cardiovascular disease and myocardial infarction." (PMID 37663661, 2023). "Baseline characteristics of the cohort of 4561 post-myocardial infarction patients according to four categories of cystatin C-based estimated glomerular filtration rate (eGFR)." (PMID 28182761, 2017). "In the present study, we found that several previously reported biomarkers were detected to be upregulated, including CRP, NGAL, and Cystatin C. CRP was first identified as a biomarker of inflammation and high concentrations are associated with mortality in patients with acute myocardial infarction." (PMID 35087594, 2022). "There were significant differences regarding total cholesterol, triglyceride, high-density lipoprotein, low-density lipoprotein, cystatin C, eGFR and GS among stable angina pectoris (SAP), unstable angina group (UAP), and acute myocardial infarction (AMI) patients." (PMID 33466214, 2021).
amyloidosis (20 papers, 2005 to 2025). A disorder characterized by the localized or diffuse accumulation of amyloid protein in various anatomic sites. "Genetic polymorphisms of cystatin C are associated with AD, while the L68Q mutation leads to hereditary cerebral hemorrhage with amyloidosis of the Icelandic type, where cystatin C and β-amyloid co-deposit in cortical blood vessels." (PMID 40626308, 2025). "Associated with amyloidosis, CST3 was also found upregulated in AMD compared to DR, but higher levels were found in RRD." (PMID 36875133, 2023). "Mutations in CST3 genes were associated with an increased risk of developing nAMD and hereditary cerebral haemorrhage with amyloidosis." (PMID 36875133, 2023). "A similar effect to what has been described for the pathogenic mutation CST3 p.L68Q, causative for hereditary cerebral haemorrhage with amyloidosis, Icelandic type (HCHWA-I), resulting in increased intracellular localization of the mutant Cystatin C58." (PMID 32345996, 2020). "A point mutation in the cystatin C gene is responsible for the dominantly inherited icelandic type of amyloidosis, hereditary cystatin C amyloid angiopathy (HCCAA; Olafsson and Grubb, 2000)." (PMID 26696821, 2015). "In addition, a point mutation in the cystatin C gene causes a particularly dominantly inherited type of amyloidosis: the hereditary cystatin C amyloid angiopathy (HCCAA;)." (PMID 35740133, 2022). "Mutations in CST3 can cause amyloidosis characterized by deposition of abnormal protein fibrils." (PMID 34551193, 2021). "Cystatin C, with an AmyloGram score of just 0.73, and transthyretin (0.74) are directly responsible for two well-known amyloidoses." (PMID 41099342, 2025). "Hereditary amyloidosis comprises more than 30 subtypes, including TTR, ApoA-I, ApoA-II, gelsolin, lysozyme amyloidosis, cystatin C amyloidosis (ACys), fibrinogen Aα-chain, β2-microglobulin, ApoC2-II, and ApoC39." (PMID 39152105, 2024). "Mutant variants of CST3 form deposits with APP peptides in senile plaques and arteriolar walls in the brain of AD patients, suggesting a role in amyloidosis." (PMID 36875133, 2023). "The same approach was successfully applied to cystatins, especially for postulating the mechanisms of amyloidosis of human cystatin C as well as human lysozyme." (PMID 15904486, 2005). "These endogenous inhibitors provide an important regulatory mechanism for CTSS and this is highlighted by the fact that abnormal formation of cystatin C, which is a condition known as hereditary cystatin-C amyloid angiopathy, results in cerebral hemorrhage with amyloidosis." (PMID 32398133, 2020). "Some inconsistency in the amyloidosis as a cause of inhibitory activity of human cystatin C in our mutation optimization may be due to lack of the data of single-site mutation in the strand domain of the cystatin sequence." (PMID 15904486, 2005). "SAA receptors, such as SELS (glucose homeostasis and ER stress), ABCA1, ABCA7, SCARB1 (cholesterol efflux), CD36, TLR2, TLR4, CST3 (inflammatory signaling), FPR2 (chemotaxis and immune cell activation), and AGER (amyloidosis), have been reported previously." (PMID 27799725, 2016). "In the case of human cystatin C, the decrease in strand along with an increase in helix might have prevented amyloidosis, despite the fact that helix change was not always as evident as in the case of lysozyme." (PMID 15904486, 2005).
end-stage renal disease (20 papers, 2014 to 2025). "Cystatin C alone or in combination with creatinine was reported to strengthen the association between the eGFR and the risks of death and end-stage renal disease in general-population or CKD." (PMID 35585568, 2022). "A key future direction involves health economic studies to demonstrate that the long-term benefits of earlier CKD detection and intervention with cystatin C, such as reduced progression to end-stage renal disease and lower healthcare costs, outweigh the initial higher test cost." (PMID 41503314, 2025).